RN7SKP211 (RN7SK pseudogene 211)
Gene: Miscellaneous RNA gene on chromosome 6 (105,904,373 to 105,904,687, forward strand). Ensembl gene ENSG00000200198.
Homologues: Orthologues: chimpanzee 7SK (97% identical), guinea pig 7SK (68% identical). Paralogues in human: RN7SKP255 (76% identical), 7SK (75% identical), RN7SKP9 (75% identical), RN7SKP217 (75% identical), RN7SKP203 (74% identical), RN7SKP250 (74% identical), RN7SKP243 (74% identical), RN7SKP133 (73% identical), RN7SKP294 (73% identical), RN7SKP79 (73% identical), RN7SKP90 (73% identical), RN7SKP102 (73% identical), and 284 more.